PLK4 (polo like kinase 4)
Diseases named in the same sentence as PLK4 in open-access papers (continued):
Sharing a sentence is not in itself a finding about the gene and the disease.
cancer (continued). "From authors’ perspective, Plk4 might represent a valuable tumor biomarker and critical target for cancer diagnosis and therapy." (PMID 33777739, 2021). "Given that PLK4 is a centriole-associated factor, it was not surprising to learn that PLK4 is proproliferative in vascular fibroblasts, as observed here, and in cancer progression, as previously reported." (PMID 33778212, 2021). "Although the increase and decrease of Plk4 expression have been reported in many tumor types, no Plk4 recurrence/driver mutation was found in the genome sequencing of cancer cells." (PMID 33777739, 2021). "Plk4 dysregulation was found to be related to the onset and progression of various cancers." (PMID 33777739, 2021). "Thus, Plk4 has received the priority concern because it is recognized as a bridge between centrosomes and cancer." (PMID 33777739, 2021). "Thus, KLF14 transcriptionally repressed Plk4 and played a role in preventing centriole duplication in human cancer cells." (PMID 33777739, 2021). "Recent studies showed that Plk4 is an important anti-apoptotic molecule in cancer cells." (PMID 33777739, 2021). "In addition, abnormal expression of the Plk4 in cancer is often correlated with aberrant promoter methylation." (PMID 33777739, 2021). "The role of Plk4 in cancer invasion and metastasis has been well documented." (PMID 33777739, 2021). "PLK4 drives epithelial-mesenchymal transition of cancer cells, cancer cell motility and migration." (PMID 34065956, 2021). "Taken together, the role of Plk4 in cancer cell proliferation is well established." (PMID 33777739, 2021). "PLK4 inhibitors would potentiate aneuploidy and genomic instability and lead to cancer cell death." (PMID 34778045, 2021). "Similarly, Plk4 was widely overexpressed in most cancerous tissues than in normal tissues because of the active proliferation and division of cancer cells." (PMID 33777739, 2021). "To date, three different small molecule inhibitors selectively target polo-like kinase 4 with nanomolar affinity and block cell proliferation in a number of human cancer lines, including osteosarcoma, cervical carcinoma, and breast, lung, and colon cancer cells, likely via centrosome depletion." (PMID 32873708, 2020). "The polo-like kinase 4, which initiates centriole duplication by controlling SAS-6 localization to the site of organelle assembly, is considered a promising target for cancer therapy where the underlying causes of the disease involve centrosome overamplification." (PMID 32873708, 2020). "Plk4 can also promote cancer invasion and metastasis through regulation of the actin cytoskeleton." (PMID 32807875, 2020). "In addition, FAM46C restrained cancer cell invasion and suppressed MDA MB-435 cancer growth in a xenograft model, opposing the effect of Plk4." (PMID 32807875, 2020). "This led scientists to propose PLK4 inhibition as possible anti-cancer treatment." (PMID 30604763, 2019). "This study uncovers the mechanism underlying Plk4 activation and may offer strategies for anti-Plk4 intervention against genomic instability and cancer." (PMID 31672968, 2019). "There is abundant evidence that the alteration of PLK4 levels and activity may play a general driver role in cancer and that PLK4 expression is deregulated in many cancer types." (PMID 31035417, 2019). "Furthermore, overexpression of PLK4 promoted, while knockdown of PLK4 suppressed cancer cell proliferation, migration, and invasion." (PMID 31489978, 2019). "Furthermore, Cep131 overexpression contributes to excessive recruitment of STIL to the centriole, which stabilizes Plk4, leading to centrosome amplification and cancer development." (PMID 31358734, 2019). "Thus, Cep131 phosphorylation by Plk4 is critical for centrosome amplification and for cancer progression." (PMID 31358734, 2019).
cancer (continued). "Moreover, Cep131 overexpression caused excessive STIL recruitment, concurrently accumulating and stabilizing Plk4 and leading to centrosome amplification and cancer development." (PMID 31358734, 2019). "Recently, it has been demonstrated that PLK4 enhances cancer cell invasion and Hela cells could be regulated from a classic mesenchymal to a more epithelial phenotype by down-regulating PLK4 expression." (PMID 29352113, 2018). "In present study, we found the commonly upregulated PLK-4 expression in TCGA Pan-cancer analysis." (PMID 30315225, 2018). "Therefore, there is an evolving trend of PLK4 up-regulation in diverse cancers and promising responses to treatment of such tumors with PLK4 inhibitor drug candidates such as CFI-400945." (PMID 29340047, 2017). "Thus, we implicate the protein-protein interactions of PLK1 and PLK4 in the maintenance of mutant KRAS-expressing cancers, and illustrate the use of compounds that block these interactions in single-agent or combination therapies." (PMID 28807782, 2017). "In this scenario, induction of polyploidy by inhibiting PLK4 may represent a new approach to cancer therapy." (PMID 29340047, 2017). "We therefore further examined the correlation between KLF14 and Plk4 in human cancers." (PMID 26439168, 2015). "Finally, we have provided a perspective on role of PLK4 signaling in cancer and the potential avenues that may be the subject of analysis for future studies." (PMID 41488365, 2025). "Interestingly, PLK4-Wnt/β-catenin crosstalk has been reported in other cancers as well." (PMID 40940791, 2025). "However, the molecular mechanism of PLK4 in these cancers needs further investigation." (PMID 41488365, 2025). "Thus, PLK4 plays an integral role in supporting centrosome activity, and its dysregulation triggers genomic instability that may result in cancer development and progression." (PMID 41488365, 2025). "Studies in different cancers suggest that PLK4 may regulate the tumor immune microenvironment." (PMID 41092110, 2025). "PLK4 is not an often-mutated gene in neoplasms; however, its overexpression has been associated with cancer, and it is being widely investigated as a therapeutic target for cancer management." (PMID 41488365, 2025). "Therefore, targeting the pathways that regulate PLK4 could provide new approaches to treating cancers characterised by centrosome amplification." (PMID 40710347, 2025). "A recent study identified over-elongation of centrioles in a variety of human cancer cell lines as another possible cause of CA: overly long centrioles fragment after PLK4 inhibition, which can lead to CA in the absence of centriole biogenesis, confirmed at an ultra-structural level." (PMID 39285247, 2024). "Thus, the knowledge that the PLK4-specific inhibition is a promising strategy for enhancing effects of RT can be further utilized to investigate and develop multimodality treatment approaches in breast and potentially other cancers." (PMID 38365710, 2024). "In addition, a bioinformatic analysis suggested that PLK4 may be a key oncogene of EC that acts by regulating cancer stem cell characteristics." (PMID 38326803, 2024). "Thus, the combination of PLK4 inhibition with RT might synergize in dysregulation of centrioles leading to, compared to single-agent treatment, further genomic instability of cancer cells and enhanced antiproliferative effects." (PMID 38365710, 2024). "Therefore, CFI-400945 represents one of the PLK4 inhibitors that is readily translated into real clinics and will be thoroughly evaluated in the follow-up clinical trials to treat oxaliplatin-resistant cancers." (PMID 38951519, 2024). "Furthermore, PLK4 expression levels have been reported to be significantly higher in malignant tumor samples, with this overexpression constituting a biomarker predicting meagre prognosis for many human cancers." (PMID 37173887, 2023).
cancer (continued). "Since there is differential protein secretion in cells with centrosome amplification via Plk4 overexpression, we decided to investigate whether high Plk4 expression would also play a role in potentiating paracrine anoikis resistance of cancer cells in the tumor microenvironment." (PMID 36797240, 2023). "Moreover, high expression of PLK4 endows cancer cells with invasive and metastatic abilities." (PMID 35670224, 2022). "In addition, although high expression of PLK4 has been linked with an aberrant centrosome number in several cancers, the high expression of PLK4 did not result in abnormal centrosome amplification in KFs in this study." (PMID 35670224, 2022). "Therefore, inhibition of PLK4 might be a new strategy for the treatment of many cancers, including AML (Zhao and Wang." (PMID 36051696, 2022). "Hence, PLK4 has been considered as a therapeutic target for treating various cancer." (PMID 35387563, 2022). "Several studies have shown that PLK4 inhibition may lead to cancer cell death." (PMID 35387563, 2022). "The ability of TRIM37 to prevent the formation of ectopic PLK4-containing aggregates is particularly important in the context of cells lacking functional centrosomes, suggesting for example that TRIM37 could trigger selective mitotic failure in cancer types sensitive to PLK4 inhibition." (PMID 35136173, 2022). "However, our understanding of PLK4 aberrant expression in cancer development is far from adequate, and more research is needed to investigate the novel mechanisms of their involvement in maintaining genomic stability and new strategies for AML targeted therapies." (PMID 36051696, 2022). "Thus, Plk4 has emerged as a pivotal player in cancer development." (PMID 33777739, 2021). "Due to the close association between embryonic development and tumorigenesis in terms of genes, proteins, metabolic levels and important biological behaviors, we have a hypothesis that SNP rs2305957 might be used as a biological biomarker for activation of Plk4 gene in cancer development." (PMID 33777739, 2021). "Therefore, Plk4 has received extensive attention as a biomarker and a target for cancer treatment." (PMID 33777739, 2021). "Moreover, the expression level of Plk4 varied in different cancers." (PMID 33777739, 2021). "Distinct from its canonical rate-limiting role in the control of centriolar duplication, non-centriolar PLK4 has also been implicated in actin-dependent cancer cell migration and invasion, cell protrusion, and invasion and metastasis in model cancer xenografts." (PMID 32501498, 2020). "Additionally, PLK4 was also proved to mediate drug resistance in cancers." (PMID 32536824, 2020). "Furthermore, the FAM46C/Plk4 ratio declined markedly with advancing clinical cancer stage." (PMID 32807875, 2020). "Besides cancer, PLK4 aberrations also contribute to other human diseases." (PMID 31035676, 2019). "Suppression of PLK4 activity may offer a novel strategy for human cancer therapy." (PMID 30337519, 2018). "Interestingly, overexpression of PLK4 mRNA has been observed in several cancer types." (PMID 30068345, 2018). "STIL could also have an indirect effect on cancer, as a downstream effector of PLK4." (PMID 29352115, 2018). "Furthermore, Cox regression analysis suggested PLK4 as an independent prognostic factor, indicating that PLK4 may be a pivotal modulator involved in cancer development." (PMID 22829937, 2012).
cancer (continued). "Furthermore, combination treatments of PLK4 inhibitors with other therapeutic agents in breast and other cancers might be of value, especially to augment tumor responses to immunotherapy in patients with metastatic breast cancer, an approach that is already being implemented in clinical trials." (PMID 41092110, 2025). "To date, several PLK4 inhibitors, including CFI‐400945, Centrinone, Centrinone B, YLT‐11, and YLZ‐F5, have been characterized in cancer cell lines and in vivo xenograft models." (PMID 40257113, 2025). "The overexpression of Plk4, the kinase upstream of SAS-6, has been shown to promote centrosome amplification, chromosomal instability, and cancer cell invasion." (PMID 40825584, 2025). "Despite being known for its potential among other PLK types (PLK2, PLK3, PLK4, and PLK5), PLK1 is determined recently as a potential oncogenic target across various cancer types due to its extensive research exploration and essential mitotic roles." (PMID 41404416, 2025). "FOXM1 binds largely to the proximal promoter regions of PLK4 and VEGF of the different cancer cell lines analyzed (ECC1, MCF-7, and SK-N-SH)." (PMID 38338955, 2024). "Our results support further mechanistic and translational studies of anti-PLK4 agents and RT as a novel multimodality combination treatment strategy in TNBC and potentially other cancers." (PMID 38365710, 2024). "Despite a large amount of prior work in other cancer models, questions remain as to the selectivity of CFI for PLK4 over other kinases and especially Aurora B4,28,37,38." (PMID 36934096, 2023). "Based on the data from various cancer types obtained from TCGA, we used the GEPIA2 program to analyze the differences in PLK4 mRNA levels." (PMID 36620611, 2022). "Tumor microenvironmental hypoxia induces the HIF-1α-dependent overexpression of PLK4, AURORA A, and CYCLIN D, resulting in CA in a wide range of cancer types." (PMID 36012111, 2022). "Polo-like kinase 4 (PLK4), a key regulator of centriole biogenesis, is frequently overexpressed in cancer cells." (PMID 36051696, 2022). "We found that the inhibition of IL17RA and PLK4 significantly blocked the proliferation of normal keratinocytes and SCC cancer cells in in vitro studies." (PMID 36009523, 2022). "Plk4 inhibitors (CFI-400945) has been shown in several studies to be synergistic with the chemotherapy drugs, antagonism, and irradiation in cancers." (PMID 33777739, 2021). "Plk4 overexpression induces CA and may promote carcinogenesis, suggesting that Plk4 is a therapeutic target for cancer." (PMID 33777739, 2021). "More importantly, deregulation of genes in this module including PLK4, AURKB, DAAM1 and DAAM2 are correlated with aggressive forms of human cancer." (PMID 31142743, 2019). "In all cases, motility was only blocked by co-inhibition of PLK4 and AURKB/C, indicating these kinases are functionally redundant in a variety of cancer contexts." (PMID 31142743, 2019). "Interestingly, association of POLQ overexpression with increased somatic mutation load and PLK4 overexpression has been observed in other many cancer types, suggesting that POLQ overexpression may be involved in the pathogenesis of diverse human cancers." (PMID 31137743, 2019). "Although miR-126 expression has been reported previously in other human cancers, ours is the first study that provides a novel and comprehensive insight into the functional role of miR-126 in HCC by directly targeting PLK-4." (PMID 30315225, 2018).
cancer (continued). "A small molecule Plk4 inhibitor, CFI-400945 (an ATP competitive inhibitor), was tested in patient-derived mice xenografts (against a range of cancer types) and significantly reduced tumour growth and increased overall survival." (PMID 29757235, 2018). "In the present study, we found that PLK4 was markedly downregulated in both HCC cell lines and fresh cancer tissues, using quantitative real-time-PCR and western blot." (PMID 22829937, 2012). "Other candidates, such as SMARCA1, KDM6B, IRF2, PLK4, and HUWE1, may well have functional relevance to cancer development in particular cancer types, and be worthy of further investigation." (PMID 40514689, 2025). "Inhibition of PLK4 activity by various compounds such as centrinone, centrinone B, CFI-400945, YLZ-F5, and RP-1664 has been shown to confer antitumorigenic effects and sensitize cancer cells to various chemotherapeutic drugs, targeted therapies and radiation." (PMID 41092110, 2025). "Polo-like kinase 4 (PLK4), a member of the PLK family, is essential for faithful centriole duplication, which, when dysregulated, contributes to genomic instability, cell cycle disruption, and cancer development." (PMID 41488365, 2025). "As centrosome amplification has been observed in almost all types of cancer and centrosomes cannot duplicate in the absence of PLK4, PLK4 has emerged as a key target." (PMID 40710347, 2025). "PLK4 mRNA expression showed a significant negative correlation with its methylation levels, which were markedly lower in cancer tissues compared to normal tissues." (PMID 41488365, 2025). "Polo-like kinase 4 (PLK4) serves as a marker for tumor features and poor outcomes in cancers." (PMID 38326803, 2024). "Indeed, PLK4, a member of the PLK family, has been clarified to affect the proliferation ability and metastatic potential of cancer cells via distinct mechanism." (PMID 37324947, 2023). "Remarkably, we found that PLK4 expression was dramatically enhanced in the tumor tissues compared with the adjacent non-tumor tissues in most cancer types, including CRC." (PMID 37324947, 2023). "The expression level pattern of PLK4 between tumor and adjacent non-tumor tissues was first analyzed with TCGA Pan-cancer datasets." (PMID 37324947, 2023). "Not surprisingly, the misregulation of Plk4 leads to serious mitotic defects, including chromosome segregation and centrosome number alterations, common hallmarks of cancer cells." (PMID 36768356, 2023). "Evidence has indicated that some PC-related protein dysfunction could promote cancer development, such as PLK1, PLK4, AURKA, and so on." (PMID 37101292, 2023). "Furthermore, in a mouse xenograft model of human cancer using MDA MB-435 cells, FAM46C inhibited tumor progression in opposition to Plk4." (PMID 32807875, 2020). "PLK4 is overexpressed in numerous cancer types, although its expression does not always correlate with CA." (PMID 31506331, 2019). "The results demonstrated that PLK-4 expression was commonly upregulated in TCGA Pan-cancer compared with non-tumor tissues, especially in HCC." (PMID 30315225, 2018). "Yet a recent study with a highly specific chemical inhibitor of PLK4, another critical centriolar replication factor, demonstrated that cancer cells can survive without centrioles." (PMID 28423708, 2017). "Roles of PLK4 in various nonbreast cancer malignancies and its potential as a biomarker." (PMID 41092110, 2025). "In addition, Polo-like kinase 4 (PLK4), a kinase that promotes SAS-6 recruitment to the cartwheel structure, is overexpressed in cancer leading to centrosome amplification, increased cell invasion, and increased small vesicle secretion." (PMID 40825584, 2025). "The negative linkage of PLK4 with survival in many cancers has been reported." (PMID 38326803, 2024).